SHBG (sex hormone binding globulin)
Diseases named in the same sentence as SHBG in open-access papers (continued):
Sharing a sentence is not in itself a finding about the gene and the disease.
Hepatic steatosis (32 papers, 2016 to 2025). Steatosis is a term used to denote lipid accumulation within hepatocytes. "Some studies confirmed that in the overweight population, increased visceral adipose tissue and increased stage of hepatic steatosis were connected with decreased SHBG production, which leads to increased risk of DM2 development." (PMID 40427034, 2025). "The complex relationship between SHBG, BMI, and age highlights the importance of considering both hormonal and metabolic factors when assessing fatty liver risk." (PMID 39768643, 2024). "Previous research has also reported that reduced SHBG levels increase the risk of hepatic steatosis or elevated ALAT levels." (PMID 38816662, 2024). "All of the predictors, except the presence of fatty liver, demonstrated a positive relationship with SHBG, indicating that higher values were associated with increased SHBG levels." (PMID 39768643, 2024). "The insights from this study on SHBG, BMI, and blood pressure emphasize the importance of considering a range of metabolic factors when assessing fatty liver risk." (PMID 39768643, 2024). "Low SHBG levels have been linked to metabolic dysfunction, suggesting a potential role as an indicator of fatty liver risk." (PMID 39768643, 2024). "An increase in one unit of SHBG was associated with a 12.5% reduction in the odds of fatty liver (OR: 0.875, 95% CI: 0.786–0.974)." (PMID 39768643, 2024). "Previous literature has shown that lower endogenous SHBG level is associated with higher risk of cardiometabolic disorders and fatty liver, and this association is reported to be constant in both sexes across age groups." (PMID 37900132, 2023). "In particular, low SHBG more than testosterone levels seem to be associated with hepatic steatosis, suggesting that bioavailable, free testosterone and SHBG levels can be considered early biomarkers for NAFLD development." (PMID 34572151, 2021). "The same meta-analysis concluded that increasing SHBG concentrations in both sexes independently lowered the risk of hepatic steatosis." (PMID 29590099, 2018). "This inverse relationship between SHBG and insulin is particularly pronounced among women with greater liver fat accumulation, suggesting a compounded metabolic risk in the presence of both hepatic steatosis and decreased SHBG." (PMID 41586225, 2025). "Metabolic associated fatty liver disease (MAFLD) correlates strongly with low levels of SHBG." (PMID 39139216, 2024). "Additionally, the genetic determinants of SHBG overlap with those of other metabolic risk factors for fatty liver, as captured in our MR analysis." (PMID 37900132, 2023). "Fatty liver disease with decreased SHBG levels may play a causative role in the development of PCOS in adolescents." (PMID 33139661, 2020). "It is intriguing to consider whether SHBG may mediate the association of active HCV with less hepatic steatosis and whether the post-SVR decline in SHBG may affect a patient’s risk of developing NAFLD after SVR." (PMID 32128321, 2019). "Therefore, the suppression of hepatic SHBG release in the context of MAFLD may play a role in the causative pathway for hepatic steatosis in this condition, and contribute towards worsening of hepatic IR." (PMID 37367914, 2023). "Besides, our data support that fatty liver is perhaps an influencing factor for the association of serum SHBG level with MS in that when the parameter of NAFLD was added into our linear regression model, the association turned to be no longer statistically significant." (PMID 29109457, 2017). "This indicates that for every 5-unit decrease in SHBG, the likelihood of developing fatty liver decreased by about 48.7%." (PMID 39768643, 2024). "The t-test results indicate a statistically significant difference in SHBG levels between the healthy and the group of participants diagnosed with fatty liver." (PMID 39768643, 2024).
Hepatic steatosis (continued). "This study highlights a significant association between low SHBG levels and the presence of fatty liver disease (MAFLD), demonstrating that SHBG serves as an important indicator of fatty liver in a metabolically compromised population." (PMID 39768643, 2024). "Our research contributes to identifying SHBG as a potential biomarker for fatty liver disease and metabolic health." (PMID 39768643, 2024). "Overexpression of SHBG suppresses lipogenesis and thereby can diminish the development of hepatic steatosis." (PMID 37367914, 2023). "Our complementary observational and MR results support suggestive causal associations between SHBG with liver fat, particularly in women, indicating that interventions targeting this pathway, along with management of accompanying risk factors, may help the prevention of fatty liver." (PMID 37900132, 2023). "In fact, the overexpression of SHBG results to protect obesity-prone db/db mice from HFD-induced hepatic steatosis, even after ORX." (PMID 34572151, 2021). "We showed that circulating total testosterone levels were decreased, while serum SHBG levels were increased in proportion to the grade of hepatic steatosis among male CLD-C patients." (PMID 30487676, 2018). "In human liver tissues, SHBG and HNF4α mRNA expression decreased along with the elevated grade of hepatic steatosis." (PMID 30455723, 2018). "Thus, a decrease in SHBG by five units significantly reduced the odds of developing fatty liver disease." (PMID 39768643, 2024). "Sex hormone-binding globulin (SHBG), on the other hand, a liver derived protein that transports sex hormones in the blood and affects their bioactivity, has been associated with lower odds of fatty liver in both men and women in a recent meta-analysis." (PMID 37900132, 2023). "In this study, we firstly aimed to investigate the cross-sectional and longitudinal association of serum sex hormone levels (e.g. T, DHEA) and SHBG with the fatty liver index (FLI), a validated non-invasive and cost-efficient tool for the estimation of fatty liver in population-based studies." (PMID 37900132, 2023). "We found that 4 of 16 patients with SHBG > 42.35 had liver steatosis." (PMID 36140294, 2022). "SHBG = 42.35 allows prediction of liver steatosis for PDFF > 5.56%." (PMID 36140294, 2022). "Our results revealed that HNF4α and SHBG mRNAs were significantly lower in subjects with high grades of hepatic steatosis, in accordance with a significantly decreasing trend in serum SHBG levels along with the elevated severity in our NAFLD subjects diagnosed by ultrasonography." (PMID 30455723, 2018). "Research on liver specimens showed that not only did serum concentrations of SHBG decrease as the degree of hepatic steatosis exacerbated in NAFLD patients but also the liver mRNA expression of SHBG was negatively correlated with the severity of liver injury and intrahepatic TG." (PMID 30455723, 2018). "Furthermore, we found that hepatic SHBG mRNA expression in 32 liver biopsy samples decreased as the grade of hepatic steatosis elevated." (PMID 30455723, 2018). "Additionally, as the concentration of serum SHBG significantly decreased with the elevated degree of liver steatosis and injury, it can potentially be used to monitor the clinical response to interventions in the management of patients with NAFLD." (PMID 30455723, 2018). "Our studies indicated that serum SHBG, but not testosterone, is associated with fatty liver or other metabolic disorders." (PMID 29109457, 2017). "However, it is important to emphasize that SHBG acts as an indicator rather than a predictor, as the observed associations are based on individuals already diagnosed with fatty liver." (PMID 39768643, 2024). "In addition, circulating SHBG increased with lifestyle modifications including diet control and aerobic exercise, and the response to increasing SHBG correlated more strongly with decreasing liver steatosis than with visceral adiposity." (PMID 30374329, 2018).
Hepatic steatosis (continued). "However, several studies have highlighted the relationship between low SHBG with fatty liver." (PMID 29109457, 2017). "We found that 3 hormones acted as mediators between BMI and hepatic steatosis in both men and women: 17α-hydroxyprogesterone, FSH, and SHBG." (PMID 41261677, 2025). "Overexpression of SHBG, by creating a double transgenic mouse (SHBG-C57BL/ksJ-db/db), in a NAFLD model or in a diet–induced model of hepatic steatosis, significantly reduced liver fat accumulation through PPARγ modulation." (PMID 33854482, 2021). "In this model, the estimate for fatty liver was −12.80 (p < 0.0001), indicating that individuals with fatty liver have SHBG levels approximately 12.8 units lower than those without the condition." (PMID 39768643, 2024). "In contrast, the presence of fatty liver again had a significant negative impact on SHBG levels." (PMID 39768643, 2024). "The SHBG is not a statistically significant parameter to predict liver steatosis." (PMID 36140294, 2022). "SHBG is not a statistically significant parameter in the prediction of liver steatosis." (PMID 36140294, 2022).
osteoporosis (29 papers, 2015 to 2025). A condition of reduced bone mass, with decreased cortical thickness and a decrease in the number and size of the trabeculae of cancellous bone (but normal chemical composition), resulting in increased fracture incidence. "The relationships between circulating SHBG level and risk of osteoporosis weren’t consistent in published studies." (PMID 40713573, 2025). "A cross-sectional study among 404 Chinese middle-aged and elderly men reported that high SHBG was an independent risk factor of osteoporosis/osteopenia after adjustment for E2 and T." (PMID 40713573, 2025). "Multiple observational studies reported significant associations between circulating SHBG levels and osteoporosis or fracture risk, aligning with our MR study findings." (PMID 40713573, 2025). "As a diagnostic tool for osteoporosis or osteopenia, SHBG would act more as an adjunct or a supplementary test, rather than a replacement for BMD or DXA." (PMID 38116310, 2023). "Two studies in Chinese and US populations showed an increased risk of osteoporosis with increased SHBG levels." (PMID 35925966, 2022). "Our research determined the causal link between circulating SHBG, which could either work as sex hormone transporter or function beyond the role of sex hormone, and risk of osteoporosis under the two-sample MR analysis framework." (PMID 40713573, 2025). "Thus, study like randomized controlled trial (RCT) is needed to establish a definitive causal link between SHBG level and osteoporosis." (PMID 40713573, 2025). "Our result can be helpful for researchers to identify new treatment target for osteoporosis, or reminding clinicians of taking measures and concerted efforts to prevent or intervene with bone loss when patients are diagnosed as high circulating SHBG level." (PMID 40713573, 2025). "This study also found that an increase in SHBG leads to an increased risk of osteoporosis." (PMID 40078581, 2025). "In addition, the partly surprising links between total T, higher risk for osteoporosis and lower risk for statins seen in standard MR in males appeared attributable to SHBG." (PMID 36653534, 2023). "Haplotype CCGGT (consisting of rs11078701C, rs1017163C, rs9898876G, rs62059836G, and rs2541012T) and haplotype CGGT (consisting of rs858521C, rs858518G, rs6259G, and rs727428T) in SHBG and neighboring genes have been associated with a significant risk effect for osteoporosis in Chinese men." (PMID 36388878, 2022). "SHBG levels have been linked to a number of diseases, including osteoporosis." (PMID 35925966, 2022). "This body evidence indicates that SHBG might play an important role in the development of osteoporosis, although this association may be influenced by skeletal site and age." (PMID 34717706, 2021). "Furthermore, studies have linked lower SHBG levels to several aging‐related disorders that affect various biological pathways, such as dementia, vascular disorders, and osteoporosis." (PMID 29075555, 2017). "Foremost, our result can be helpful for researchers to develop new treatment target for osteoporosis, or reminding clinicians of taking measures and concerted efforts to prevent or intervene with bone loss when patients are diagnosed as high circulating SHBG level." (PMID 40713573, 2025). "A previous study identified that a higher SHBG level may be a risk factor for osteoporosis." (PMID 34717706, 2021). "MR utilizes genetic variants as instrumental variables to test the causal effect of an exposure (e.g., circulating SHBG level) on an outcome (e.g., BMD or osteoporosis risk)." (PMID 40713573, 2025). "The serum testosterone concentration decreases with age, while the SHBG levels increase, which is related to many diseases, including osteoporosis." (PMID 37248448, 2023). "Here, we found that SHBG was negatively associated with spine, hip and femoral BMD and the presence of osteopenia/osteoporosis and that it was positively associated with VFs." (PMID 34460073, 2022).
osteoporosis (continued). "And women in the highest quartiles of SHBG were older with greater prevalence of osteoporosis and high PTHi and β-CTX levels." (PMID 25968889, 2015). "Comparison of patients according to quartiles of SHBG levels showed that women in the highest quartiles were older with high prevalence of osteoporosis, and high PTHi, β-CTX levels." (PMID 25968889, 2015). "The comparison result showed that the plasma levels of ALP, SHBG, and OC were significantly higher in the osteoporosis group than in the other groups, but the levels of the FAI were significantly lower in the osteoporosis group compared to the other groups." (PMID 31105806, 2015). "BMI was also inversely associated with osteoporosis, HDL-c, cholesterol, LDL-c, and SHBG." (PMID 40498079, 2025). "In future researches, the role of circulating SHBG in osteoporosis could be prioritized aiming to investigate its biological effects on bone health and underlying mechanism, finally to develop targets for prevention and therapeutic intervention." (PMID 40713573, 2025). "Further exploration of the potential mediator between circulating SHBG concentration and osteoporosis also may be meaningful." (PMID 40713573, 2025). "Substantial observational evidences demonstrates that endogenous sex steroid hormones (not only serum testosterone (T) and estradiol (E2) but also their transporter - sex hormone-binding globulin (SHBG)) are closely associated with the occurrence and development of osteoporosis." (PMID 40713573, 2025). "Seventh, MR study performed by other groups pointed out that SHBG was closely linked to osteoporosis risk specifically in female population but not in males." (PMID 40713573, 2025). "We also detected suggestive associations to bone strength and injury risk in both sexes, but with the exception of SHBG and osteoporosis in females (HR = 1.08, p = 0.00015), none of these findings survived correction for multiple testing." (PMID 36653534, 2023). "The study used summary statistics from large-scale genome-wide association studies (GWAS) conducted for SHBG, a protein modulating the concentration and bioavailability of sex hormones and heel-estimated BMD (eBMD), a widely accepted metric for osteoporosis management and fracture risk assessment." (PMID 38203403, 2023). "While certain studies propose that elevated SHBG levels in men could elevate osteoporosis and fracture risks, even after accounting for sex hormone levels, other research has found no significant impact of SHBG on BMD after considering other factors." (PMID 38116310, 2023). "For FA-BMD, higher SHBG and TT levels might reduce FA-BMD and were recognized as risk factors for osteoporosis (P<0.05, after FDR control)." (PMID 35925966, 2022). "Some studies have shown that a higher level of SHBG is a risk factor for osteoporosis and fractures, independent of sex steroid levels." (PMID 36388878, 2022). "In conclusion, by MR approach analysis, we identified SHBG and TT levels as potential causal risk factors for BMD loss in men that may increase the incidence rate of osteoporosis." (PMID 35925966, 2022). "SHBG play a role in numerous diseases, containing osteoporosis in postmenopausal women." (PMID 33535639, 2021). "We believe the finding of SHBG may be helpful in elaborating the low bone mineral density in CS patients when taking into account the reported role of SHBG in osteoporosis." (PMID 28944995, 2018). "Likewise, “Evans and al” found a significant increase in SHBG levels in 81 men with both idiopathic osteoporosis and fractures as compared with 68 healthy controls." (PMID 31105806, 2015). "Previous research reported the negative association between SHBG and osteoporosis." (PMID 40278612, 2025).
osteoporosis (continued). "BMI was also inversely associated with age at recruitment, osteoporosis, hay fever and allergic rhinitis or eczema, high-density lipoprotein cholesterol (HDL-c), cholesterol, low-density lipoprotein cholesterol (LDL-c), sex hormone binding globulin (SHBG), and total testosterone." (PMID 40498079, 2025). "However, higher SHBG and TT levels might reduce HE-BMD and were recognized as risk factors for osteoporosis (P<0.05, after FDR control)." (PMID 35925966, 2022). "Hoppe and al suggest that the SHBG level may be a marker for the severity of osteoporosis, because they found in a study of 184 osteoporotic women having a mean age of 76 years, that plasma SHBG levels were associated with the presence of one or more VFs and with the number of prevalent fractures." (PMID 25968889, 2015). "This study aims to bridge this gap by investigating the correlations between SHBG levels, testosterone and other sex hormones with BMD in middle-aged Saudi men, thereby providing valuable insights to enhance osteoporosis prevention and management strategies." (PMID 38116310, 2023). "A previous cross-sectional study of 142 Moroccan men with no prior diagnosis of osteoporosis reported that BMD at the total hip was negatively correlated with SHBG." (PMID 35669686, 2022). "Furthermore, the SNP rs8178616 mapped to the PROS1 gene was found to be correlated with SHBG and eBMD, giving rise to the hypothesis that PROS1 may play a role in the pathogenesis of osteoporosis." (PMID 38203403, 2023).